RN7SKP168 (RN7SK pseudogene 168)
Gene: Miscellaneous RNA gene on chromosome 2 (17,122,841 to 17,123,140, reverse strand). Ensembl gene ENSG00000222842.
Homologues: Orthologues: chimpanzee 7SK (98% identical), guinea pig 7SK (48% identical). Paralogues in human: RN7SKP79 (69% identical), RN7SKP269 (67% identical), RN7SKP176 (67% identical), RN7SKP85 (67% identical), RN7SKP8 (67% identical), RN7SKP150 (66% identical), RN7SKP249 (66% identical), RN7SKP78 (66% identical), 7SK (66% identical), RN7SKP174 (66% identical), RN7SKP180 (66% identical), RN7SKP202 (66% identical), and 283 more.